IL5 (interleukin 5)
Diseases named in the same sentence as IL5 in open-access papers (continued):
Sharing a sentence is not in itself a finding about the gene and the disease.
infection (continued). "Splenocytes removed from infected animals and stimulated in vitro with a total parasite extract (FhTE) produced high levels of IL-4, IL-5 and IL-10, with significant higher levels of IL-4 and IL-10 as soon as the first wpi, reaching a plateau at week 2 after infection." (PMID 26720149, 2015). "Interestingly, stimulation with TsCE, but not rTsCRT, resulted in increased synthesis of both IL-4 and IL-5 mRNA upon infection." (PMID 25811778, 2015). "Conversely to what has been shown for E75CV1 the progression of the E75-infection resulted in a dramatic imbalance of the immune system by day 7 pi, with the significant up-regulation of 9 genes, namely: IL-5, IL-1β, IL-6, IL-8, IL-10,IL-21, IL-23, DEFB2 and TLR-3." (PMID 26589145, 2015). "One of the most interesting findings of this study is the observation that fexofenadine treatment caused significant reductions in circulating IgE levels and splenocyte production of IL-5 and IFNγ as well as increased numbers of eosinophils at the site of infection." (PMID 26204515, 2015). "Moreover, the number of IL-5- and IL-13-producing CD4 T cells was significantly (p<0.01) reduced in FI-RSV-immunized STAT6-deficient mice at day 7 post-infection." (PMID 25769044, 2015). "Splenocytes from ST2 deficient mice had no impaired production of IL-4, IL-5, IL-10 or IFNγ following ConA stimulation and this was throughout infection." (PMID 24663956, 2014). "Next, we investigated whether there were changes in the cytokine milieu at the site of infection using the thoracic cavity lavage and assessed the levels of several cytokines: IL-4, IL-5, IL-13, IL-25, IL-33, and IFNγ." (PMID 24663956, 2014). "In contrast to these studies, ablation of IL-5 either through genetic manipulation or antibody treatment has shown little effect on parasite burdens in Schistosoma mansoni, Trichinella spiralis or Trichuris muris infection." (PMID 25028340, 2014). "However, at day 3 post-infection, the Socs4R108X/R108X mice showed significantly higher levels of cytokines and chemokines, such as IL-1β, IL-4, IL-5, IL-6, IL-12p40, IL-13, IFN-γ, and KC (CXCL1), MIP-2 (CXCL2) and MCP-1 (CCL2), respectively." (PMID 24809749, 2014). "A careful analysis of the systemic (serum) cytokine levels in mice chronically infected with the Omani isolate revealed that type 1 (IFN-γ, TNF-α, GM-CSF), type 2 (IL-5, IL-13, to a lesser degree IL-4), and type 17 (IL-17) cytokines coexisted throughout the infection." (PMID 25398130, 2014). "The IL-4, IL-5, IL-9, and IL-13 pretreatment responses were subtracted from 1 year posttreatment responses, and correlations between the changes and pretreatment infection intensity, a proxy of the amount of worm-derived antigen exposure upon treatment, were calculated." (PMID 24357629, 2014). "Accordingly, the markedly diminished level of detectable IL-5 protein during the latter days following infection could reflect consumption of the cytokine by one or more cell types infiltrating the infected lungs." (PMID 24068930, 2013). "Using a mouse model of influenza virus infection, we found a robust transient release of IL-5 into infected airways along with a significant and progressive accumulation of eosinophils into the lungs, particularly during the recovery phase of infection, i.e. following virus clearance." (PMID 24068930, 2013). "IL-5 alone has been shown to control adult worm development in primary infection." (PMID 22348321, 2012). "In contrast to what occurred in neonates, infection of infants altered hematopoietic cells to increase the severity of AAD in later-life by increasing Th2 (IL-5 and IL-13) cytokine release from MLN cells, MSC numbers, transpulmonary resistance and IL-13 production in the lung." (PMID 22870337, 2012). "Larvae recovered 70 days post infections in IL-4R-/-/IL-5-/- DKO were from the heart and muscles." (PMID 22348321, 2012). "Thus, filarial lymphedema with active infection is characterized by elevated plasma levels of IL-5, IL-13, and TGF-β." (PMID 22679524, 2012).
infection (continued). "Interestingly, there were also significant increases in the concentrations of the Th2-type cytokines IL-4 and IL-5 in DR1 mice after PR8 infection." (PMID 22457834, 2012). "Post-hoc comparisons showed significantly elevated production of GM-CSF (P = 0.005), IL-2 (P = 0.008), and IL-5 (P = 0.03) in the chronic infection compared to uninfected groups and elevated production of IL-5 (P = 0.03) and IL-10 (P = 0.0008) in the chronic versus light infection groups." (PMID 21666788, 2011). "However, we found that in both SHIV162p3 and SIVmac251 infected macaques, both Th-1 (IL-2, IFN-γ) and Th-2 (IL-4, IL-5, IL-6, IL-10, and IL-13) type cytokines were markedly elevated after infection." (PMID 21464951, 2011). "For 6 of the cytokines measured [IL-1a, IL-5, IL-10, IL-12(p40) and IL-12(p70)], the concentration in the supernatant dropped to a level which was below the detection limits for the particular assays by 15 min post H37Rv-infection." (PMID 22039457, 2011). "In studies of infection by Fasciola hepatica and S. mansoni, the secreted antioxidant, peroxiredoxin (Prx), was shown to induce Ym1-expressing AAMs, which enhanced the secretion of IL-4, IL-5 and IL-13 from naïve CD4+T cells." (PMID 21246055, 2011). "However, when age was combined with infection status, IL-5 declined over time in egg-positive people, while increased with age in the egg-negative group." (PMID 21039611, 2010). "At face value, the increased total production of Mf in these mice rejects the adaptive phenotypic plasticity hypothesis, which predicts that control mice should produce as many or more Mf over the course of infection in comparison with IL-5–treated mice." (PMID 20976100, 2010). "Infection with T. canis induced elevated levels of IL-4, IL-5, and IL-10 compared to control mice." (PMID 20544012, 2010). "for example, IL10 helps to control excessive T helper 1 and CD8+ T cell responses that contribute to the immunopathology associated with infection; it also prevents the overproduction of IL4, IL5, and IL13, which can lead to severe fibrosis during the T helper 2 response." (PMID 20398313, 2010). "To test this hypothesis, we analyzed the levels of IFN-γ and IL-5 in sera of infected mice at different time points after infection." (PMID 19621080, 2009). "Finally, to confirm the association of Retnla with eosinophils, we infected WT C57BL/6 and IL-5−/− mice with S. mansoni and then examined the expression of Retnla mRNA in the liver at 9 and 12 wk post-infection." (PMID 19381262, 2009). "Similarly, the cytokines Il1α, Il5, Il6, and Il12 were secreted into the broncho-alveolar space of both strains after infection but were higher in DBA/2J mice." (PMID 19293935, 2009). "We were unable to detect the secretion of IL-4 or IL-5 during any stage of the infection." (PMID 18544042, 2008). "Taken together, these results show that the IL-10 responses develop early compared to the IL-5 response and may be down-modulating immunopathological responses that occur during the early phase of infection." (PMID 18045464, 2007). "This might also explain the lag between the age profiles of IL-5 levels and infection intensity we observed in this study." (PMID 18045464, 2007). "A recent rhinovirus experimental infection study has supported this hypothesis by observing impaired virus clearance and increased symptoms in subjects with increased IL-5/IFN-γ mRNA ratios in induced sputum." (PMID 16001979, 2005). "Furthermore, earlier work reported repressed IL-5 expression in the porcine lung during L3 passage, followed by a strong upregulation at day 14 and the maintenance of elevated IL-5 expression until at least 4 weeks post infection." (PMID 40808955, 2025). "The significance of ILC2s activation during CR infection could lie in production of IL-4 and IL-13 to drive mucus production, in addition to IL-5 which can act synergistically with IL-4 to influence or enhance an antibody response, promoting bacterial clearance." (PMID 40591723, 2025).
infection (continued). "However, the polarized type 2 response (IL-4, IL-5, IL-9, and IL-13) might reduce the severity of infection and contribute to the nematode parasite's eradication." (PMID 39103392, 2024). "IL-5, IL-4, and IL-3 could attenuate the anti-Candida response in the WT-infected group, and a combination of both allows the fungal cells to thrive and induce tissue damage and death within 8 days of WT infection." (PMID 38783167, 2024). "Furthermore, NK cell depletion reduced serum IL-5, IL-10, and G-CSF on day 6 p.i, suggesting that NK cells may interact with other innate immune cells or endothelial cells during the early infection for regulating cytokine production." (PMID 38743761, 2024). "High infection intensity of S. mansoni should be probably controlled by a major locus SM1 mapped to chromosome 5q31-q33 that contains three cytokine genes notably Interleukin 4 (IL4), Interleukin 13 (IL13) and Interleukin 5 (IL5) that are implicated in the Th2 immune response." (PMID 36889485, 2023). "However, previous systematic reviews and clinical trials about CRSwNP treatment with anti-IL-5 found no increase in the risk of infection." (PMID 36498632, 2022). "Therefore, further work is required to determine whether NK cell-secreted IL-5 is a direct recruiter of eosinophils during in vivo infection." (PMID 36238293, 2022). "Moreover, ILC2-producing IL-5 and IL-13 were markedly increased in PreF- and PreFAlum-immunized sero- compared to sero+ dams, suggesting that prior infection mitigated the ILC2 response following RSV challenge." (PMID 36268035, 2022). "High levels of IL-5 and TNF suggested that the children may be suffering from morbidity associated with S. mansoni, especially due to the fact that most children had heavy infection intensities before treatment." (PMID 34239575, 2021). "Because distinct immune responses are triggered against different life cycle stages of filarial parasites, we scrutinized whether either IL-4R–dependent or IL-4R–independent/CCR3- or IL-5–dependent immunity was also operating at the level of stage-specific mf infections." (PMID 32571840, 2020). "In murine models, infection with helminths led to the reduction of Bacteroidales and the concurrent expansion of Clostridiales communities, which was hypothesized to stimulate an anti-inflammatory response (increased IL-5 and IL-13) in the host." (PMID 32450885, 2020). "In the current study, we explored the long-term consequences of IL-4Rα deficiency and degree of eosinophil recruitment on B. malayi filarial parasitism using a typically nonpermissive BALB/c mouse model of infection and additional IL-5 and CCR3 compound deficiencies." (PMID 32571840, 2020). "Although IL-5 serum levels in infected tumor-bearing mice were not increased enough to be statistically significant, we observed an increase in this cytokine associated with the infection." (PMID 32547942, 2020). "After stratifying by Plasmodium infection density, submicroscopic infection was associated with increased peripheral concentrations of IFN-α and decreased concentrations of IL-6, while microscopic infections were associated with elevated levels of TNF, IL-10 and IL-5." (PMID 32365058, 2020). "The stronger type 2 (IL4 and IL5) response and reduced abundance in the dual infection can be considered analogous to increased population mortality due to predation, which in turn could have led to the higher reproductive allocation and more eggs found in utero." (PMID 31871660, 2019). "However, the levels of IFNγ, IL-4 and IL-5 were elevated in Stat2−/− mice during super-infection." (PMID 30337919, 2018). "In addition, we found a higher relative production of Th2 cytokines (IL5, IL13) in response to mitogen stimulation (expressed as cytokine response ratio) rather than the lack of cytokine response to be associated with increased risk for infection." (PMID 29051761, 2017).
infection (continued). "Interestingly, the IL-5 signalling pathway was the only cytokine signalling pathway identified as being downregulated during acute infection, which could be due to the skewing towards a Th1 response." (PMID 28938907, 2017). "To exclude the possibility that eosinophils contributed to the phenotype, we repeated the infection studies in Il5−/− mice, which have severely reduced pulmonary eosinophilia, and could not identify any differences in bacterial counts or the inflammatory response elicited by AMs in vitro." (PMID 28228256, 2017). "To investigate how IL-33 might interfer with the host immune response, we measured the levels of the key Th1 cytokines (IFN-γ, IL-12 and TNF-α), key Th2 cytokines (IL-4, IL-5 and IL-13), and the regulatory cytokine IL-10 in the serum at various time-points after infection with PbA." (PMID 25659095, 2015). "On the other hand, the tempo of eosinophil accumulation and increased IL-5 production during the resolution phase of infection raises the possibility that this type 2 response could have a positive role in restoration of pulmonary architecture and function by promoting tissue repair." (PMID 24068930, 2013). "Here we have shown a boost in plasma IL-5 levels 24-hr after human S. haematobium infections are treated with praziquantel, and that this is dependent on both the intensity of the pre-treatment infection (or antigen dose the individual is exposed to by treatment) and pre-treatment levels of SWA-IgE." (PMID 23556029, 2013). "The production of IL-4, IL-5, IL-6, and IL-10, which in turn promote B-cell proliferation and antibody production, is the cause of susceptibility of dogs, which become not able to control the infection." (PMID 22400039, 2012). "Alternatively, the observed association of IL4 polymorphism and infection intensities could be due to linkage disequilibrium of IL4 with other genes such as IL13 and IL5, which in humans are located just 12.5 kb and 132 kb upstream of IL4 and are also key TH2 cytokines." (PMID 21501512, 2011). "The STH infection effect (combined light and chronic infection groups) was associated with greater production of GM-CSF (P = 0.02) and IL-2 (P = 0.004) and the chronic STH infection effect with greater levels of GM-CSF (P = 0.007), IL-2 (P = 0.03), IL-5 (P = 0.01), and IL-10 (P = 0.01)." (PMID 21666788, 2011). "The relatively low concentrations of IL-12, IL-5 and IL-4 may reflect that probably these cytokines are needed in very minute amounts, present only very temporarily or are gradually degraded or consumed by cells earlier after response to infection." (PMID 20546583, 2010). "As previous studies have shown that sterile immunity in schistosomiasis is dependent on IgE levels, eosinophils and on the Th1/Th2 balance, our laboratory decided to test whether any allelic variants in the IL4, IL5 and IL13 genes would predispose individuals to high infection levels by Schistosoma." (PMID 19471606, 2008). "Bov342 infection resulted in upregulation of CXCL1, whereas VN1203 resulted in IFN-γ, IL-2, IL-5, and IL-10." (PMID 40410375, 2025). "In the mock infection group, however, the Winter PM exposure induced elevated IFN-γ, IL1-β, IL-8, IL-4, IL-5, IL-10, and VEGF-A at the 24 h timepoint." (PMID 40671793, 2025). "Of the gene markers analyzed, male TLR7ko mice only showed significant increases in IL5 and IRF7 expression following infection." (PMID 40143355, 2025). "We observed that nine biomarkers (fractalkine, IFNγ, IL-5, IL-6, IL-10, IL-12, IL-13, IL-21, and TNFα) had significantly increased levels post-infection with subtype C HIV-1 compared to the pre-infection levels." (PMID 40862133, 2025). "The expression of GM-CSF, IL-4, IL-5, IL-10, IL-13, KC, and VEGF in Th2 cells, and IL-2, IL-4, IL-5, IL-10, and IL-17 in NK cells significantly increased after infection (PBS-treated group)." (PMID 39264964, 2024).
infection (continued). "Concurrently, the cytokine expression profile demonstrates a gradual elevation in IL5, IL13, IFNγ, and TNF, indicating an increasingly complex immunomodulatory environment according to the infection dose." (PMID 39621794, 2024). "The infection model in goats was established and validated by the fecal egg count (FEC) test and qPCR analysis of the gene expression of IL-5 and IL-6." (PMID 38786064, 2024). "In mice, infection with N. brasiliensis results in ILC2 and eosinophil recruitment to the FRT and increased IL-4, IL-5, and IL-33 in the tissue and/or lavage." (PMID 38277692, 2024). "Quantification of the expression of six inflammatory markers (IL-5, IL-8, IL-22, CCL20, TIMP1, CSF2) was carried out at 2, 24, and 48 hr post-infection." (PMID 37218575, 2023). "Buffaloes with both primary and secondary infection of F. gigantica also showed a mixed Th1/Th2 response in serum with elevated IFN-γ, IL-4, IL-5, and TGF-β during the early stages of infection." (PMID 38149297, 2023). "More importantly, both SARS-CoV-2 and pCoV-GD01 infection induced the production of cytokines such as IFN-gamma, IL-12p70, IL-13, IL-2, IL-5, TNF-alpha, IL-17A, IP-10, MCP-3, MIP-1beta, MIP-2, Exotaxin, IL-15/15R, IL-28, IL-3, G-CSF, IL-1alpha and ENA-78." (PMID 37330497, 2023). "Significantly higher SARS-CoV-2 antigen-specific IgG, IFN-γ, IL-5, TNF-α, and IL-6 levels occurred in the breakthrough infection group compared to the booster immunization group (p = 0.013, 0.039, 0.024, 0.017, and 0.039, respectively)." (PMID 37515030, 2023). "Thus, the selective deletion of IL-5+ ILC2s in the R5: Gata3f/f mice, or the conditional ablation of Tslp from dermal TRMs in the Ccl24-cre: Tslpf/f mice, in each case resulted in decreased numbers of ILC2s, eosinophils and dermal TRMs in the lesions, and ameliorated the infection outcome." (PMID 38030609, 2023). "At visit 1, increased levels of IL-4 and IL-5 were observed in patients who required ICU admission (Group 2), but these levels had fallen one month after the infection (visit 2) (p = 0.039 and p = 0.011, respectively)." (PMID 36975498, 2023). "Our study revealed top 8 cytokines (IL-17, IL-1α, IL-2, IL-10, IL-5, IFN-γ, TNF-α and IL-6) and their biomarker abilities to discriminate different stages of infection." (PMID 36646786, 2023). "P. micra infection was found to up-regulate the expression of IL-5 (P=0.0001), IL-8 (P=0.0001), CCL20 (P=0.0001), and CSF2 (P=0.0001) at 2 hr post-infection." (PMID 37218575, 2023). "In another study, upregulation of Th1 cytokines [IFN-γ, interleukins (IL)-2 and IL-12p40] and Th2 cytokines (IL-4, IL-5, IL-13 and IL-10) was thought to play a crucial role in driving cellular immune responses against IBDV in the acute phase of infection." (PMID 37744374, 2023). "Echinococcus granulosus s.s. has been shown to regulate host immunity by biasing a Th1/Th2 response towards a chronic Th2 response, as the infection was found to induce a marked increase in the transcriptional levels of IFN-γ, IL-2, IL-4, IL-5, and IL-10." (PMID 36289514, 2022). "During the whole infection time, IFN-γ played a role mainly before 90 dpi and anti-inflammatory factor IL-4, IL-5 and IL-10 were up-regulated at or after 90 dpi, indicating a response shift from Th1-orientation to Th2-orientation." (PMID 35639780, 2022). "Wild type BALB/c pups had peak levels of IL-13, IL-5 and IL-4 in the BALF at day 27 post infection with P. murina." (PMID 34682248, 2021). "Compared to RV-A1B, RV-C15 infection induced significantly higher mRNA expression of CXCL1, CXCL2, IL-5 and IL-13." (PMID 33968043, 2021). "RV-C15 infection induced airway expression of IL-25, IL-33 and TSLP, innate cytokines responsible for activation of IL-5- and IL-13-producing ILC2s expansion." (PMID 33968043, 2021). "The concentrations of IL-4, IL-5, TNF, and IFNγ in the BALF of BALB/c pups were also higher, though not statistically different, than in C57BL/6 pups at day 27 post-infection (Figure A2E–G)." (PMID 34682248, 2021).